RBM10 (RNA binding motif protein 10)
Diseases named in the same sentence as RBM10 in open-access papers (continued):
Sharing a sentence is not in itself a finding about the gene and the disease.
breast carcinoma (10 papers, 2016 to 2025). "Similarly, low RBM10 expression is associated with poorer survival in breast cancer." (PMID 40740233, 2025). "RBM10 highly correlates with the expression of Bax, the core gene in the caspase apoptosis pathway in breast cancer." (PMID 33718153, 2021). "Previous studies identified low RBM10 expression in many tumors, including lung, pancreatic, and breast cancer." (PMID 33718153, 2021). "An SMN ASE was the focus of more detailed expression analyses, at both the RNA and protein levels, in primary fibroblasts and a breast cancer cell line with stable RBM10 knockdown (KD)." (PMID 28728573, 2017). "To further characterize the relationship between RBM10 and SMN expression, we decided to use our MCF-7 breast cancer subline with the stable RBM10 KD." (PMID 28728573, 2017). "Supporting our findings, RBM10 has been associated with increased expression of VEGF, a promoter of new blood vessel growth, in breast cancer samples." (PMID 28662214, 2017). "The expression of RBM genes (RBMX, RBM3, and RBM10) on the X chromosome, as well as the expression of apoptosis-related genes, namely Bcl-2 and Bax, was detected by differential RT-PCR in 122 cases of breast cancer." (PMID 33718153, 2021). "For a previous study, we had generated a stable RBM10 KD MCF-7 human breast cancer subline." (PMID 28728573, 2017). "Therefore, RBM10 can mediate apoptosis in breast cancer cells, suggesting that it may be a useful target for breast cancer therapies." (PMID 33718153, 2021). "The analysis of the CPTAC database showed that in comparison with the surrounding healthy tissues, RBM10 protein level was considerably increased in UCEC, breast cancer, colon cancer, KIRC, OV, HNSC, LUAD, GBM, and hepatocellular carcinoma (HCC)." (PMID 39282149, 2022). "Paradoxically, expression of RBM10 (like its paralogue, the tumor suppressor RBM5) is elevated in some cancers, such as multiple endocrine neoplasia type 1, breast cancers, liver and colon cancers and some metastatic melanomas." (PMID 28728573, 2017). "When human breast carcinoma MDA-MB-231 cells are spreading on collagen-coated coverslips, endogenous FilGAP and RBM10 were localized at the cell periphery with tyrosine-phosphorylated proteins." (PMID 26751795, 2016).
pancreatic cancer (9 papers, 2015 to 2025). "Although RBM10 has been shown to play an anti-tumour role in pancreatic cancer 22, 23, its precise underlying mechanisms remain poorly understood." (PMID 40740233, 2025). "In the analysis of 109 cases of pancreatic cancer where RBM10 mutations were present, tumors were all of a high grade, pT3 stage, and harbored lymph node metastasis in three of four cases." (PMID 33718153, 2021). "The studies reviewed here have shown that deletion or mutation of RBM10 is associated with the occurrence and poor prognosis of human cancers, including lung and pancreatic cancer." (PMID 33718153, 2021). "Our study explores the relationship between RBM10 and pancreatic cancer immunity, showing that RBM10 loss may influence PD-1 expression in NK cells through the JAK-STAT pathway, potentially contributing to tumour immune escape." (PMID 40740233, 2025). "Mutations in RBM10 are found in a third of cancers, including colon and pancreatic cancer." (PMID 33718153, 2021). "Finally, high RBM10 expression was associated with a favourable prognosis in pancreatic cancer patients, suggesting that RBM10 inhibits pancreatic cancer progression by suppressing tumour immune escape through JAK-STAT-mediated regulation of PD-1 expression in NK cells." (PMID 40740233, 2025). "Furthermore, whole-exome sequencing of pancreatic cancer indicated that in 75% of these cases, RBM10 mutations were associated with favorable patient prognoses, suggesting these mutations could improve the survival rate and prolong the survival period." (PMID 33718153, 2021). "The CCK-8 assay showed a significant increase, approximately 1.5 times, in the viability of PATU-8988 and PANC-1 cells following RBM10 knockdown, suggesting successful knockdown and promotion of pancreatic cancer cell proliferation (P < 0.05)." (PMID 40740233, 2025). "We observed attenuated killing of RBM10-knockdown pancreatic cancer cells by NK cells, accompanied by upregulated PD-1 expression." (PMID 40740233, 2025). "Our results confirmed that the expression of phosphorylated JAK1 (P-JAK1), phosphorylated JAK2 (P-JAK2), and phosphorylated STAT3 (P-STAT3) was upregulated in pancreatic cancer cells following RBM10 knockdown." (PMID 40740233, 2025). "The current study investigates the role of RBM10 in pancreatic cancer progression and immune regulation." (PMID 40740233, 2025). "Subsequently, to confirm the effector function of NK cells against pancreatic cancer, particularly in the context of RBM10 expression, we co-cultured NK cells with RBM10-knockdown pancreatic cancer cells." (PMID 40740233, 2025). "Validating these findings, we found that genes encoding for the splice factors RBM10, SF3B1, and U2AF1 are also frequently mutated in the Pancreatic Cancer Canadian (PACA-CA) cohort." (PMID 37823551, 2023). "Additionally, IHC staining of 30 pairs of cancerous and para-cancerous tissues from PAAD patients showed that RBM10 expression was reduced by approximately 15% in pancreatic cancer tissues compared to para-cancerous tissues (P < 0.05)." (PMID 40740233, 2025). "Therefore, we aimed to investigate the biological function of RBM10 in pancreatic cancer and the potential mechanisms through which it operates." (PMID 40740233, 2025). "To determine whether regulation of the JAK-STAT pathway is essential, we added the JAK pathway inhibitor AZD1480 to the culture medium of RBM10-knockdown pancreatic cancer cells in vitro." (PMID 40740233, 2025). "Additionally, the killing effect of NK cells on RBM10-knockdown pancreatic cancer cells was restored in response to treatment with the JAK pathway inhibitor." (PMID 40740233, 2025). "Given that activation of the JAK1 and JAK2 pathways has been demonstrated to inhibit tumour cell susceptibility to NK cells by upregulating PD-L1 expression 39, we further investigated the activation status of the JAK-STAT pathway in RBM10-knockdown pancreatic cancer cells." (PMID 40740233, 2025).
pancreatic cancer (continued). "Our current study demonstrated reduced RBM10 expression in human pancreatic cancer tissues." (PMID 40740233, 2025). "However, it remains unclear whether reduced RBM10 expression leads to or results from inhibited NK cell infiltration in pancreatic cancer." (PMID 40740233, 2025). "Notably, RBM10 regulates hTERT gene splicing and inhibits pancreatic cancer progression." (PMID 38431575, 2024). "Thus, further studies clarifying the relationship between RBM10 and NK cell infiltration, particularly its impact on cytotoxicity in vivo and in vitro, could provide valuable insights for developing novel targeted therapies for pancreatic cancer." (PMID 40740233, 2025). "Understanding the mechanistic interplay between RBM10, the JAK-STAT pathway, and NK cell function offers a promising avenue for the development of targeted therapies to manage pancreatic cancer." (PMID 40740233, 2025). "RT-qPCR and Western blot analyses of these manipulated cells showed that the expression of RBM10 was higher in PATU-8988 and PANC-1 pancreatic cancer cells compared to other cancer cell lines." (PMID 40740233, 2025). "Understanding the mechanistic interactions between RBM10, the JAK-STAT pathway, and NK cell function provides a promising avenue for developing targeted therapies for pancreatic cancer." (PMID 40740233, 2025). "Previously, the correlation of the RBM10 expression with tumor stages was reported to be negative in pancreatic cancer." (PMID 39282149, 2022).
colorectal cancer (7 papers, 2017 to 2025). A primary or metastatic malignant neoplasm that affects the colon or rectum. "In addition to the tumors studied above, RBM10 is commonly mutated in colorectal cancer and also plays an important role in colon cancer." (PMID 33718153, 2021). "Previous studies have identified RBM10 as a tumor suppressor gene in various cancers, including lung, liver, breast, pancreatic, and colorectal cancers." (PMID 40941029, 2025). "RBM10 mutation is considered to be one of the most common mutation genes in solid tumors, including LUAD, colorectal cancer, bladder cancer, and pancreatic ductal adenocarcinoma." (PMID 39282149, 2022). "RBM10 is abnormally expressed in the lung, breast, and colorectal cancer, female genital tumors, osteosarcoma, and other malignant tumors." (PMID 33718153, 2021).
endometrial cancer (6 papers, 2021 to 2025). Primary or metastatic malignant neoplasm involving the endometrium (mucous membrane that lines the endometrial cavity). "RBM10 is also downregulated in endometrial carcinomas and can regulate the selective cleavage of VEGFA, thus affecting angiogenesis." (PMID 33718153, 2021). "Similarly, RBM10’s effect on NUMB exon 9 splicing was observed in endometrial cancer where it has also been shown that miR-355 can impact overall RBM10 levels." (PMID 39863103, 2025). "Additionally, miR-335 overexpression regulates the expression of Numb-L in endometrial carcinoma by targeting RBM10, providing a new biomarker for the diagnosis of endometrial cancer." (PMID 33718153, 2021). "In endometrial cancer, AS of vascular endothelial growth factor A (VEGF-A) is regulated by RBM10." (PMID 35836577, 2022).
small cell lung carcinoma (5 papers, 2017 to 2023). Small cell lung cancer (SCLC) is a highly aggressive malignant neoplasm, accounting for 10-15% of lung cancer cases, characterized byrapid growth, and early metastasis. "RBM10 is regarded as a tumor suppressor, but recent studies have shown that in small cell lung cancer, RBM10 has a reversed exertion with endogenous RBM5 deletion." (PMID 37426488, 2023). "In addition, the analysis of the Cancer Cell Line Encyclopedia (CCLE) database indicated that RBM10 had the highest expression in small-cell lung cancer (SCLC) cells and the lowest in HNSC cell lineage." (PMID 39282149, 2022).
cardiac hypertrophy (4 papers, 2018 to 2021). "RBM10 is a Star-PAP-associated protein that is required for the regulation of mRNAs involved in cardiac hypertrophy." (PMID 34576144, 2021). "Star-PAP has been shown to affect APA in cardiac hypertrophy through an association with the RNA binding protein RNA binding motif protein 10 (RBM10), which stimulates Star-PAP polyadenylation activity." (PMID 32560344, 2020). "In heart disease, the deletion of RBM10 can cause H9c2 cell hypertrophy, while the splicing-independent function of RBM10 controls specific 3′UTR processing that regulates cardiac hypertrophy and can be reversed by ectopic inhibition of RBM10." (PMID 33718153, 2021). "Down-regulation of RBM10 during cardiac hypertrophy and heart failure controls expression and CPA of cardiac mRNAs through the promotion of Star-PAP use of distal PASs and increased poly(A) tail length." (PMID 32560344, 2020). "We have identified another unique Star-PAP coregulator RNA binding protein (RBM10) that functions with Star-PAP, and together they regulate cardiac hypertrophy (unpublished data)." (PMID 29203642, 2018).
osteosarcoma (4 papers, 2021 to 2025). A usually aggressive malignant bone-forming mesenchymal neoplasm, predominantly affecting adolescents and young adults. "Overexpression of RBM10 reduces proliferation, colony formation, migration, and invasion of osteosarcoma cells." (PMID 40740233, 2025). "RBM10 induces apoptosis in U2OS cells (osteosarcoma) by suppressing Bcl2 expression, promoting caspase-3 activity, and increasing TNF production." (PMID 40740233, 2025). "The expression of RBM10 protein can reduce the proliferation of primary chondrocytes by inducing apoptosis in osteosarcoma cells through inhibiting the expression of Bcl-2, and promoting the expression of caspase-3 as well as the production of TNF-α." (PMID 33718153, 2021). "RBM10 overexpression can reduce the proliferation and colony formation of osteosarcoma cells and inhibit migration and invasion." (PMID 33718153, 2021). "RBM10 overexpression induced osteosarcoma cell apoptosis via the inhibition of Bcl-2, the activation of caspase-3, and the transcription and production of TNF-α." (PMID 34804951, 2021).
thyroid cancer (4 papers, 2017 to 2025). "In thyroid cancer, particularly in aggressive and metastatic forms, the loss of RBM10 has been identified as a significant factor in promoting tumor progression and metastasis." (PMID 39874138, 2025). "This suggests that collectively, these three exon inclusion isoforms were the key targets through which RBM10 loss promotes the metastatic spread of thyroid cancers." (PMID 39874138, 2025). "Furthermore, using human thyroid cancer cell lines, they demonstrated that RBM10-mediated splicing of VCL, CD44 and FN1 enhanced cell migration and invasion." (PMID 39874138, 2025). "In order to understand which pathways are connected with wild-type RBM genes in thyroid cancer, we first randomly built RBMX and RBM10 gene regulatory network (fold-change cutoff: 2; p-value <0.05) using human PTC samples from TCGA (The Cancer Genome Atlas)." (PMID 29156680, 2017).
cholangiocarcinoma (3 papers, 2022 to 2025). A carcinoma that arises from the intrahepatic biliary tree (intrahepatic cholangiocarcinoma) or from the junction, or adjacent to the junction, of the right and left hepatic ducts (hilar cholangiocarcinoma).
colon cancer (3 papers, 2021 to 2025). "Additionally, many other driver genes are frequently mutated in colon cancer, such as ARID1A, SOX9, FAM123B, BCL9L, RBM10, CTCF, and KLF5." (PMID 34912802, 2021).
lymph node metastasis (3 papers, 2015 to 2025). "Remarkably, RBM10 mutations were associated with enhanced survival, although all RBM10-mutated cases were of high grade, pT3 stage and harboured lymph node metastasis in three of four cases." (PMID 25855536, 2015). "Thus, mutations in RBM10 are associated with tumor stage, lymph node metastasis, and poor survival rate, and therefore, there is potential in exploring the use of RBM10 as a biomarker for the progression and prognosis of LUAD." (PMID 33718153, 2021). "Using data from PAAD patients in the TCGA database, RBM10 expression was found to be associated with patients' T stage, clinical stage, and age (all P < 0.05), but not with lymph node metastasis, distant metastasis, or sex." (PMID 40740233, 2025). "For example, RBM10 mutation is significantly associated with the American Joint Committee on Cancer (AJCC) stage diagnostics, lymph node metastasis, and male patients, but not with smoking, age, tumor size, or differentiation." (PMID 33718153, 2021).
pancreatic ductal adenocarcinoma (3 papers, 2020 to 2022). An infiltrating adenocarcinoma that arises from the epithelial cells of the pancreas. "For example, in pancreatic ductal adenocarcinoma (Panc-AdenoCA; N = 232), the addition of functional adjustment to the algorithm resulted in a gain of three additional drivers (ACVR1B, RBM10 and ZFP36L2) and the loss of one likely false-positive genes (FAU)." (PMID 32024818, 2020).
viral infections (3 papers, 2025). "RBM10, a critical RNA-binding protein and splicing regulator, modulates the expression of a wide array of cellular proteins and has been implicated in multiple pathological processes such as cancer and viral infections." (PMID 40941029, 2025). "JINR1 and its interacting protein, RBM10, are involved in the inhibition of transcription of miR-216b-5p and miR-1-3p during viral infection in SH-SY5Y cells." (PMID 40272157, 2025). "Depleting JINR1 or RBM10 during viral infection prevents the downregulation of miR-216b-5p and miR-1-3p." (PMID 40272157, 2025). "To investigate the function of RBM10 in viral infection, we conducted a series of infection assays." (PMID 40742131, 2025). "Because RBM10 not only interacts with JINR1 but also regulates its expression during viral infection, it remains unclear whether transcriptional inhibition of miR-216b-5p and miR-1-3p by RBM10 is due to its effect on JINR1 expression or its interaction with it." (PMID 40272157, 2025). "RBM10 silencing did not result in any noticeable change in the expression of primary, precursor, and mature miR-370-5p and miR-30e-3p transcripts during viral infection." (PMID 40272157, 2025).
anaplastic thyroid cancer (2 papers, 2018 to 2019). "Novel genes altered in fatal non-anaplastic thyroid cancer include MED12 mutations (14%) and RBM10 (11%)." (PMID 31835496, 2019).
atherosclerosis (2 papers, 2022 to 2025). A disease characterized by the build-up of fatty material and calcium deposition in the arterial wall resulting in partial or complete occlusion of the arterial lumen. "Several risk markers related to the immune response that have key roles in atherosclerosis were identified, including the top aging marker MMP8, disease markers KIR3DL1 and MAGEA6, network markers based on degree (RBM10, PJA2, and CMTM6), and network markers based on betweenness (IRAK1 and VAMP8)." (PMID 35706446, 2022).
bladder cancer (2 papers, 2022 to 2025). "Importantly, mutations in RBM10 and CDKN1A are also significantly more abundant in bladder cancers of men than of women." (PMID 41062697, 2025).
melanoma (2 papers, 2016 to 2017). A malignant, usually aggressive tumor composed of atypical, neoplastic melanocytes. "Therefore, altered RBM5 levels in melanoma may result in decreased translational regulation of RBM10, and thus the pro-transformation characteristics associated with RBM10 in melanomas, and here in our RBM5-null system." (PMID 28662214, 2017). "Although RBM10 is mostly localized in the nuclei in human melanoma A7 cells, forced expression of Src family tyrosine kinase Fyn induced translocation of RBM10 from nucleus into cell peripheries where RBM10 and FilGAP are co-localized." (PMID 26751795, 2016).
metastatic tumor (2 papers, 2022 to 2025). "IF of paraffin sections of brain metastatic tumors in patients with LUAD further showed increased GFAP-positive astrocytes in the lesions of patients with low RBM10 expression." (PMID 40069781, 2025).
non-small cell lung carcinoma (2 papers, 2022 to 2023). A group of at least three distinct histological types of lung cancer, including non-small cell squamous cell carcinoma, adenocarcinoma, and large cell carcinoma.
ovarian carcinoma (2 papers, 2017 to 2025). A malignant neoplasm originating from the surface ovarian epithelium. "In two breast and one of two ovarian cancer cell lines having RBM10 KD, KITLG exon 6 was preferentially included, with normal RBM10 levels associated with exon 6 exclusion." (PMID 28728573, 2017).